CXCR3 (C-X-C motif chemokine receptor 3)
Diseases named in the same sentence as CXCR3 in open-access papers (continued):
Sharing a sentence is not in itself a finding about the gene and the disease.
infection (continued). "Moreover, CCL2, CCL21, CXCL2, CXCR2, and CXCR3 mRNAs were significantly induced at 6–12 h after V. harveyi infection, implying that P. leopardus immune cells can be activated and recruited to the sites of infection at early time points post-infection." (PMID 39450165, 2024). "Furthermore, our findings indicate highly activated CXCL10 in neutrophils challenged with S. aureus challenge in vitro, consistent with previous studies observing elevated CXCL10 and CXCR3 in neutrophils during infection with Salmonella, Aspergillus, or respiratory virus." (PMID 39001897, 2024). "We therefore investigated whether the intranasal or intramuscular infection with NY-ESO-1 S-FLU virus differentially induced the expression of the molecules (VLA-1 [CD49a], CXCR6, CD103, CD44, CD49d, CCR5 and CXCR3) implicated in retention or trafficking of effector CD8+ T cells in lung." (PMID 36626205, 2023). "Furthermore, CXCL10 regulates the development and function of T cells, recruiting Th cells expressing the chemokine receptor CXCR3 (primarily Th1 cells), and stimulating the activation and migration of immune cells (such as NK cells, monocytes, and T cells) to sites of infection." (PMID 37964304, 2023). "Likewise, even during acute toxoplasmosis, the co-expression of cell surface receptors KLRG1 and CXCR3 distinguishes CD8+ T cell subsets that have memory potential or are terminally differentiated, with continued presence of infection driving the KLRG1+CXCR3- terminally differentiated population." (PMID 35727849, 2022). "Furthermore, SjS patients with either serological evidence of past EBV infection or recent infection/reactivation presented higher values of CXCR3+ CD4+ T cells (Th1) and CXCR3+ CXCR5+ CD4+ T cells (Tfh1) compared to those without serological evidence of active infection." (PMID 33603079, 2021). "Additionally, expression of CXCR3, which is associated with T cell migration, did not change in the three infection schemes including 104Pbyop1Δ-infected mice." (PMID 34025654, 2021). "We speculated that a high infection dose might result in a saturated immune response controlled by different pathways (e.g., Toll-like receptor (TLR) 2/MyD88 pathway) and this would hinder the effect of CXCR3 loss." (PMID 34835465, 2021). "Additionally, CXCR3 was down regulated and CCR4 up regulated in memory CD4+ Treg exposed to ANDV-GP VLPs, this suggest that ANDV-GP could specifically act over CXCR3 in CD4+ Treg cells potentially altering their ability to migrate to the site of infection." (PMID 32984065, 2020). "We observed that optimal CD8 T cell recruitment to the site of infection is critical for protection since CXCR3-deficient mice could not achieve complete viral clearance in their CNS." (PMID 32973802, 2020). "Thus, to understand how CXCR3+ Tregs protect against infection, we characterised the functions of them and found that more than 90% of them expressed ki67, a marker of proliferating cells, while only about 60% of CXCR3− Tregs were positive for ki67." (PMID 33014369, 2020). "However, whether NKT cells acquire CXCR3 after activation or whether a population of NKT cells already expressing CXCR3 expands after infection remains to be elucidated." (PMID 29249358, 2018). "Therefore, we wondered whether CXCR3− and CXCR3+ NKT cells would have a differential ability to produce IL-4 after infection." (PMID 29249358, 2018). "In addition, CXCR3 is also highly expressed on NK cells, plasmacytoid DCs, B cells and neutrophils and direct those cells in the localization of first-line defenders at sites of infection and inflammation." (PMID 29552679, 2017). "In addition to triggering cell migration into the brain, CXCR3 expression may provide additional B cell maturation and survival functions, which may become more apparent at the later time points as infection progresses." (PMID 27207308, 2016).
infection (continued). "We hypothesized that since KLRG1 expression and the production of IFN-γ by F3 late stage effector CD8+ T cells is IL-12 dependent, CXCR3 expression may also be IL-12 dependent, possibly explaining the attenuation of effector cells to the site of infection in our model." (PMID 26244629, 2015). "However, although CXCR3 positive T cells may promote HCV clearance in early phases of the infection, they cause tissue injury when the infection persists." (PMID 24646914, 2014). "Accordingly, it is possible that in addition to controlling T-cell recruitment to sites of infection, Cxcr3−/− T cells may undergo terminal differentiation and, possibly, premature Th1 effector death in tissues prior to mediating IFN-γ dependent inflammatory monocyte activation." (PMID 24130498, 2013). "Therefore, we examined CXCR3-GFP expression by intestinal inflammatory monocytes during infection." (PMID 24130498, 2013). "In agreement with this hypothesis, flow cytometry analysis on D15 showed an increase of CXCR3+ cells in WT mice, with a predominant recruitment of CXCR3+ iNKT cells after infection, this lymphocyte cell subset being obviously the main CXCR3+ cell subset in the liver with about 90% of positive cells." (PMID 22457760, 2012). "Our data support a novel, CXCR3-independent role for the interferon-inducible ELR- CXC chemokines in the innate host response against pulmonary B. anthracis infection that is consistent with direct chemokine-mediated antimicrobial activity at local sites of infection." (PMID 21124994, 2010). "Importantly, the levels and kinetics of expression of all CXCR3 chemokine ligands induced by acute LCMV infection was equivalent in both C57BL/6 wildtype and RIP-LCMV-GP transgenic mice indicating that CXCR3 chemokine ligands are expressed as a direct result of the infection of the pancreas by LCMV." (PMID 23675028, 2007). "Overall, children developed a SARS-CoV-2–specific CD4+ T cell response early in the course of infection with multiple effector functions, marked by potent production of IFN-γ, TNF, and IL-2, and preferential expression of CXCR3." (PMID 40906527, 2025). "CXCR3 and CCR6 were used to study the other CD4+ T-helper cell (Th) populations, in relation to the different latency profiles and infection statuses." (PMID 40963636, 2025). "Nonetheless, vaccination and infection generated BSM with different characteristics, including increased induction of a population defined by CXCR3 and CD21 expression post-infection." (PMID 40964019, 2025). "Intriguingly, both CXCR3+CCR6+ virus-specific B cells and CXCR3−CCR6+ bystander B cells are generated in the lung after infections with the influenza virus and SARS-CoV-2." (PMID 38392851, 2024). "CXCR3 is important for trafficking and recruitment of Th1 and Th17 polarized CD4+ T cells in response to infection." (PMID 38846955, 2024). "In memory CD8+ T cells, during infection, only CXCR3 presented greater expression than CCR5, while in the control group, both CXCR3 and CCR6 exhibited greater expression than CCR5." (PMID 39867906, 2024). "In Atlantic salmon, we expect that a CXCL9-11/CXCR3-dependent recruitment of Th1 type cells, T CD8+ cells, and macrophages to the infection site should help eliminate virus-infected cells." (PMID 39301034, 2024). "In our screen, all chemokine receptors showing increased PD-1 expression on day 4 post infection either match chemokines secreted by dendritic cells (CCR5, CXCR3) or respond to chemokines that also attract dendritic cells (XCR1)." (PMID 37301772, 2023). "Anti-CXCR3-blocking antibodies were intraperitoneally injected into control and IL-4C-treated mice, followed by intranasal PR8 infection (on the same day)." (PMID 38037190, 2023). "To investigate if the other CXCR3 ligand, CXCL10, or the receptor itself are contributing to murine FHL, we treated prf1−/− mice infected with LCMV to induce FHL with a CXCR3 antagonist, AMG487, starting at day 3 post infection (p.i)." (PMID 37516815, 2023).
infection (continued). "Recent studies have shown that Ly6Chi monocytes surround S. Typhimurium-confining granulomas in the spleen and recruit CD4+ T cells to the foci of infection by producing CXCL9 and CXCL10, both are ligands for CXCR3 expressed by Th1 cells." (PMID 37733817, 2023). "We proceeded to characterize CD8 T cells present in RPE/c and neural retinas on day 8 after infection using markers typically responsible for endothelial adhesion (LFA-1), retention in tissues (CD69) and migration/positioning (CXCR6, CXCR3)." (PMID 37662932, 2023). "Future clonality studies involving the LN would give more clarity to this standardization, as well as possibly incorporating markers such as CXCR3, ICOS, CD38 or HLA‐DR to identify acute specific cTfh cells after infection or vaccination." (PMID 36825370, 2023). "During peripheral infection in ganglia, the CXCL10/CXCR3 signaling pathway is indispensable for recruitment of HHV-specific CD8+ T cells and IL-15 plays an essential role in selectively activating these cells." (PMID 35337341, 2022). "Cells of the adaptive immune system such as activated T-helper type 1 (Th1) lymphocytes express CXCR3, the receptor for CXCL10, and they are recruited to the sites of infection/inflammation at least in part by CXCL10-secreting myeloid cells." (PMID 36369044, 2022). "After the first several days of infection, the percentage of CD19+/CXCR3+/CD11c+ that also expressed FCRL4 (an inhibitory receptor and EBV-induced host biomarker) progressively increased (third column)." (PMID 36248899, 2022). "While the recruitment of T-bet-expressing CXCR3+ Tregs to the site of type 1 immune responses is essential for the efficient control of these responses, it is still unknown whether the same Treg subset also exerts the tissue protective functions observed upon infection." (PMID 35572535, 2022). "Among those with detectable infection, GCs serve as the primary anatomical site of HIV persistence and the major cellular source is CXCR3 expressing Tfh cells." (PMID 35831418, 2022). "In the de novo infection context, we found that EBV increases CXCR3 (as well as CD11c and FCRL4) expression on peripheral B cells." (PMID 36248899, 2022). "As the infection progressed, these TRM cells were enriched in infection site with increased CXCR3 expression." (PMID 34707601, 2021). "However, in HIV-1 controllers, CXCR5+CXCR3+PD-1low CD4+ T cells were associated with increased HIV-1 neutralizing antibody breadth and in acute HIV infection, frequencies of CXCR3+ Tfh1 cells correlated positively with p24 plasma IgG titers at 1 year post infection." (PMID 33996678, 2021). "A TEM cell cluster in the spleen expressing Ly6C, CD27, CXCR3, and CD127 (Sp cluster 12) was more abundant in LCMV Armstrong, whereas a KLRG1+CX3CR1+ subset was more related to MCMV-GP33 infection." (PMID 33458613, 2021). "After 60 days of infection, CD8+ T-cells expressing CCR5 decreased in the blood and MLN, particularly the population of CXCR3+CCR5+ CD8+ T-cells (Student’s t-test: blood, p = 0.004; MLN, p = 0.045)." (PMID 34685494, 2021). "Recruitment and NK cells’ activation at the site of infection requires chemokines (ligands for CCR2, CCR5, and CXCR3) and cytokines (IL-12 and IL-18) secreted from myeloid cells, mainly monocytes and macrophages." (PMID 34305935, 2021). "The best model used the interaction between CXCR3 and AM3K as the predictor, demonstrating that the interaction between the numbers of Th1-type T cells and numbers of macrophages at the site of infection is a significant predictor of Johne’s disease state." (PMID 33849661, 2021). "Further, mice challenged with live MAP showed an increase in the number of CXCR3+ T cells in the lamina propria, compared to a heat-killed MAP infection group and control group." (PMID 33849661, 2021). "As infection progressed, the accumulation of CD4+ CD44hi TET+ CXCR3+ T cells increased into the lung parenchyma and airways in Mtb-infected BCG-vaccinated mice that received Z-DC transfer." (PMID 34253059, 2021).
infection (continued). "In an acute HBV infection model, the proportion and absolute numbers of CXCR3+CXCR6+ γδT cells increased on day 7 and returned to normal levels as the infection progresses." (PMID 35126348, 2021). "In Mtb-infected mice, CXCR3+KLRG1−Tbetdim T cells migrate into the lung parenchyma and control the infection, while intravascular (iv) T cells have a high expression of KLRG1, CX3CR1, and T-bet." (PMID 33879592, 2021). "Within this experimental infection model, Th2- (CXCR3− CCR6−) and Th1-cTfh (CXCR3+CCR6−) subsets were activated with different kinetics." (PMID 36845571, 2021). "Additionally, even though CXCR3+ Tregs were isolated at similar frequencies from naive or infection-experienced mice their suppressive capacity may still be different because only Tregs from infection-experienced mice had been exposed to a potent inflammatory environment." (PMID 32433493, 2020). "We found that relatively few MAIT cells expressed CCR2, CCR4, CCR6, CXCR3, CXCR4, and CCR9 in the lungs, spleen, thymus, and LP both before and after infection." (PMID 32849637, 2020). "Upregulation of ICOS, CXCR3, CXCR6, IL-18R1, and Chil3 in the brains of T. gondii-infected SCID mice that received a transfer of CD8+ immune T cells at 6 weeks after infection." (PMID 32291349, 2020). "The CXCL10 expression by MO-DCs and pDCs started very early and remained until day 20 after infection, which is consistent with the high expression of CXCR3 in specific CD8+ T cells, observed from day 5 to 30 after infection." (PMID 32574175, 2020). "Altogether, these results indicate that CXCR3 is important to specific CD8+ T cells migration into the heart of T. cruzi infected mice and to control the infection." (PMID 32574175, 2020). "This indicates that BCG prevents the recruitment of CXCR3+CD8+ T cells from the spleen, the site where immune effector cells to blood-stage infection are primed, via the blood into the brain." (PMID 33316929, 2020). "Surprisingly, on day 15 after infection, the cytotoxicity of infected specific CD8+ T cells was 100% in the isotype control group and in the anti-CXCR3 group the cytotoxicity decreased almost 50% percent when compared to the isotype control group." (PMID 32574175, 2020). "Previously, our group described that CXCR3 is critical for migration of specific CD8+ T cells into the heart during vaccination with ASP-2 and infection with T. cruzi." (PMID 32574175, 2020). "Evaluation of infection-induced changes in CD4 T cell differentiation at Day 7 revealed a strong phenotypic shift to Th1 effectors (CXCR3+), Th1 polarized Tfh cells (CXCR3 + CXCR5+) and Th1 Th17 (CXCR3 + CCR6+) CD4 T cells." (PMID 32818217, 2020). "While CXCL8/IL8 attracts neutrophils, basophils and T-cells to the site of the infection, CXCL10 is chemotactic for monocytes and T-lymphocytes by binding to CXCR3." (PMID 31619718, 2019). "In contrast, immunizations or infections that induce Th1 or Th17-polarizing inflammation are known to prime lung-homing CD4+ T cells that express CCR6 and CXCR3." (PMID 31396211, 2019). "As they have a common receptor (CXCR3), CXCL9, CXCL10, and CXCL11 have generally been studied together, and studies of combinations of CXCL9, CXCL10, and CXCL11 in infection, injury, and immunoinflammatory responses have been conducted." (PMID 31836011, 2019). "Taken together our results demonstrated that dexamethasone enhanced the expression of chemokine receptors, CXCR3, on CD8+ T cells that facilitated their migration to the infection sites to effect a better replicating virus control." (PMID 31354707, 2019). "The lymphocyte-specific chemokine receptor CXCR3 expressed by activated T cells as well as NK cells is important for CD4+ Th1 cell migration to sites of inflammation and infection." (PMID 30915078, 2019). "We also determined if CXCR3 and T-bet are co-expressed on effector CD4+Foxp3− T cells and CD4+Foxp3+ Tregs during infection." (PMID 30915078, 2019).
infection (continued). "The chemokine receptor CXCR3 expressed by activated T cells is important for trafficking of CD4+ Th1 cells to sites of inflammation and infection." (PMID 30915078, 2019). "Altogether, these results show that CXCR3 guides TEWETGQI-specific CD8+ T-cells toward the T. cruzi-infected heart tissue, and these cells play an important role controlling the infection." (PMID 31356587, 2019). "Similar to CXCR3, CCR4 is important for the migration of T cells to sites of inflammation or infection." (PMID 29760706, 2018). "Ccr5 and Cxcr3 expression was also lower in TB10.4-specific CD8+ T cells from perigonadal fat and Ccr7 remained unaffected after infection." (PMID 29040326, 2017). "An efficient antiviral response induces the recruitment of RSV-specific CD4+ and CD8+ T cells to the infection site by the CXCL9 and CXCL10 chemokines, which are induced by IFNs and the chemokine receptor CXCR3." (PMID 28751894, 2017). "We show that more IFN- secreting NK cells are detected in GT of CXCR3−/− than of WT, which likely contributes to the compensation of CXCR3 knockout mice in cleaning infection." (PMID 29552679, 2017). "We found a relative increase of Tregs expressing CXCR3 and CCR5 in HIV positive patients with early infection." (PMID 29246111, 2017). "Compared with PBS controls, sublethal infection also markedly induced mRNA levels of TLR2, IFN-γ, TNF-α, CXCL9, CXCR3, and Ang2." (PMID 28742087, 2017). "By day 15 post-infection, Zbtb32-/- P14 cells were enriched in memory precursor effector cells (MPEC; IL-7Rhi KLRG-1lo) and a greater proportion expressed CD27, CXCR3 and CD62L compared to WT controls (bottom)." (PMID 28827827, 2017). "During infection, injury, or immuno-inflammatory response, IFN-γ strongly induces the expression of CXCR3 and CXCL10 primarily on activated T cells and NK cells." (PMID 26475448, 2016). "At the earliest hours after infection, DGK activity ensured recruitment of naïve CD8 T cells to the dLNs via upregulating CCR4, CCR5, and CXCR3." (PMID 27014906, 2016). "Thus, it is expected that CXCR3 and its ligands would not only be critical for the recruitment of effector leukocytes but could also be important for the regulation of CNS physiology during CNS inflammation and infection." (PMID 27068264, 2016). "Our results showed that the majority of chemokines and receptors were up-regulated more strongly in the CVS-11 infection than the HEP-Flury at a later stage, besides CCL22, CXCR3, CXCR6, and CCR7." (PMID 27242764, 2016). "CXCR3 and its ligands (CXCL9, CXCL10, CXCL11) are thought to govern the recruitment of leukocytes to the sites of inflammation and infection." (PMID 27068264, 2016). "Generally, the fold increase of genes expressed in response to type I IFN treatment (TO-VS-IFN) was higher than the fold increase for genes expressed in response to SAV-3 (TO-VS-SAV3) infection except for the chemokines CXC10 and CXCR3." (PMID 25765343, 2015). "It has been shown that inflammatory chemokine receptors, such as CXCR3, CXCR6, and CCR5, are upregulated during infection." (PMID 26322025, 2015). "Microarray analysis revealed that the expression of CCR5, CXCR3 and CCR1 and several of their chemokines including CXCL9, CXCL10, CCL2, CCL3 and CCL9 significantly increases in response to infection in CM-affected mice." (PMID 24476686, 2014). "To investigate this further, we examined a panel of T cell activation markers (CD62L, CD69, CD44, CD25) and homing receptors (CCR5, CXCR3, CCR7) at days 5, 6 and 7 post-infection." (PMID 24809749, 2014). "CXCR3-expressing CD8+ T cells, Th1 cells and NK cells that are recruited to the site of infection contribute to CXCL10 secretion by hepatocytes via the release of IFN-γ." (PMID 24646914, 2014). "Chemokine receptor analysis revealed reduced expression of CXCR3, CCR7, and CCR6 on NK cells at early time points (days 2 and 4 after virus inoculation), followed by an increased expression of CXCR3 and CCR5 at later time points (days 7-8) of infection." (PMID 24147080, 2013).